LINC01672 (long independently transcribed non-coding RNA 1672)
Synonyms: NMR
Gene: Long non-coding RNA gene on chromosome 1 (6,724,626 to 6,730,012, forward strand). Ensembl gene ENSG00000228750.
Diseases named in the same sentence as LINC01672 in open-access papers:
LINC01672 is named in the same sentence as 2 diseases in open-access papers, as found by Europe PMC text mining. Sharing a sentence is not in itself a finding about the gene and the disease. The quoted sentences say what the papers report.
cancer (2 papers, 2022 to 2023). A tumor composed of atypical neoplastic, often pleomorphic cells that invade other tissues. "Several of these lncRNAs in the risk model have been reported to play significant roles in different cancers, such as CCR5AS, LINC01749, TMEM220-AS1, KCNMA1-AS1, SNHG1, and LINC01672." (PMID 37686677, 2023).
LINC01672 also shares sentences with these, for which no sentence is quoted: bacterial infections (1 paper).